ALB (albumin)
Diseases named in the same sentence as ALB in open-access papers (continued):
Sharing a sentence is not in itself a finding about the gene and the disease.
Hypoalbuminemia (continued). "Therefore, for patients with hypoalbuminemia who need a primary hip replacement, active treatment of concomitant diseases before operation and adequate albumin supplement in the perioperative period are helpful to reduce the risk of postoperative complications." (PMID 34526075, 2021). "However, our findings suggest that, of the many variables that can be investigated for assessing inflammation, hypoalbuminemia and lymphocytopenia (albumin and lymphocyte counts used to calculate PNI) are important variables for predicting mortality in sepsis patients." (PMID 34193271, 2021). "However, due to oxidized albumin, hypoalbuminemia in these patients may be underestimated, and increased oxidized albumin may lead to accelerated cycle between oxidative stress and neutrophil activation." (PMID 33680285, 2021). "The small but significant increase in albumin and consistent decrease in alkaline phosphatase (ALP) that we observed may provide some level of hepatoprotection as hypoalbuminemia is associated with liver fibrosis and NASH, and ALP is commonly elevated in fatty liver disease." (PMID 33802651, 2021). "In addition, we found that the subjects in the group of “normal TSAT low iron” had highest percentage of low TIBC (39.4% with TIBC < 200 μg/dL), as well as the highest percentage of hypoalbuminemia (32.7% with Albumin < 3.5 g/dL) and elevated CRP levels (40.6% with CRP > 3 mg/L)." (PMID 33863963, 2021). "Distinguishing between appropriate development of hypoalbuminemia for controlling a widespread infection and excessive capillary leakage is challenging, so treatment is often focused on addressing the underlying cause without replacing albumin." (PMID 33925831, 2021). "Moreover, hypoalbuminemia (albumin < 30 g/L) could reduce plasma osmolality and enhance the exudation within the lungs, thus, exacerbating the infection." (PMID 33892752, 2021). "Besides, the animals showed hypoalbuminemia, probably due to intestinal protein loss, but also inflammation since albumin acts as a negative acute-phase protein." (PMID 33723661, 2021). "Coincidentally, another study conducted in China also found that patients with hypoalbuminemia were at greater risk for ESRD, which may be due to the fact that MPO-ANCA was the main type of AAV and that albumin had an inhibitory effect on the binding between ANCA and its antigen." (PMID 33613528, 2020). "In inflammatory states, hypoalbuminemia may result from reduced albumin synthesis or degradation." (PMID 32982584, 2020). "These newborn patients are more likely to develop hypoalbuminemia, with many possibilities to use drugs that alter albumin binding (e.g., antimicrobial drugs, fat formulations, and indomethacin), which consequently affect bilirubin binding to albumin to result in hyper-unbound bilirubinemia." (PMID 32947818, 2020). "An explanation for such association is either that hypoalbuminemia may be a marker of inflammation as albumin is a negative acute phase reactant, or it is a reflection of renal loss of albumin and anti-thrombotic proteins creating a hypercoagulable state." (PMID 31936687, 2020). "More impressive were the results of low albumin levels (nearly 3.1 mg/dL) when simple pneumonia and pleurisy (DGR89) and pulmonary edema and respiratory failure (DRG87) occurred, underlining a possible correlation between infectious diseases and hypoalbuminemia." (PMID 33261019, 2020). "However, we substituted Child-Pugh score with surrogate markers for cirrhosis severity such as the requirement for fresh frozen plasma and albumin transfusion to indicate the patients’ coagulopathy and hypoalbuminemia, and application of which have been used in our previous works." (PMID 31581275, 2019). "Moreover, in addition to Tg, it is also known that ALB is iodinated in the thyroid gland and when ALB is elevated in blood a high protein bound iodine value can be recorded and in cases of hypoalbuminemia (low levels of ALB in blood) serum iodine levels can be reduced." (PMID 30917615, 2019).
Hypoalbuminemia (continued). "However, some studies concluded that hypoalbuminemia only becomes clinically significant at levels < 25 g/L, and that albumin replacement is only covered by health insurance in Taiwan for patients with serum albumin levels < 30 g/L and who exhibit associated comorbidities." (PMID 31253199, 2019). "Also, infection or higher levels of inflammation reflected by the higher CRP-levels in hypoalbuminemic patients could lead to capillary leakage of albumin resulting in hypoalbuminemia." (PMID 31095609, 2019). "Given that albumin is affected by protein intake and is a negative acute phase protein, we might expect to see a higher prevalence of hypoalbuminemia in BE bears due to suspected protein deficient diets and presence of chronic inflammation/infection." (PMID 31352899, 2019). "Although we did not quantify the degree of proteinuria nor measure serum albumin, our finding may be accounted for by hypoalbuminemia which has been shown to predispose to wound infection and delayed wound healing." (PMID 31223342, 2019). "In our study, the hypoalbuminemia group was older than the normal serum albumin group was and had longer anoxic time, lower incidence of initial shockable rhythm, lower mean arterial blood pressure, and higher incidence of pneumonia than did the normal serum albumin group." (PMID 31565439, 2019). "If fluid is needed at this phase, the use of albumin seems to have positive effects on vessel wall integrity facilitates achieving a negative fluid balance in hypoalbuminemia and may be less likely to cause nephrotoxicity." (PMID 29789983, 2018). "On univariate analysis, serum albumin level <3.5 g/dL was associated with longer length of stay and so when additionally controlling for hypoalbuminemia, the difference in length of stay was no longer significant (OR 2.07, 95% CI: 0.70–6.10, p = 0.19, likelihood ratio test p<0.001)." (PMID 30592736, 2018). "However, in the present study, we found that post-treatment hypoalbuminemia, but not low pre-treatment serum albumin level, was a risk factor that predicted poor outcome for mRCC patients who received sorafenib or sunitinib." (PMID 28521783, 2017). "We have shown that oxidative modifications of albumin impair its quantification by the standard laboratory albumin assay, bromo-cresol green (BCG) and the gold standard nephelometry, rendering part of the sera albumin undetected, causing apparent hypoalbuminemia in HD patients." (PMID 28542419, 2017). "Therefore, receiving infusion of albumin for the correction of hypoalbuminemia from the acute stage may be helpful in decrease HT of AIS patients after IV rt-PA." (PMID 28798356, 2017). "We could postulate that albumin replacement does not affect the long-term survival rate because it does not correct the cause of hypoalbuminemia itself." (PMID 28723973, 2017). "Therefore, post-treatment hypoalbuminemia may be a better prognostic factor which can reflect the nutritional status after targeted therapy than pre-treatment serum albumin level in patients with mRCC." (PMID 28521783, 2017). "Therefore, exogenous albumin is widely used to correct hypoalbuminaemia." (PMID 28800610, 2017). "The association between serum albumin and the severity of medication non-adherence might also be explained by the occult musculoskeletal influence introduced by hypoalbuminemia." (PMID 27326380, 2016). "However, adding GI symptom score or CRP into the multivariable regression analysis, did not attenuate the association between lower eGFR and lower albumin or hypoalbuminemia." (PMID 26651991, 2015). "Hypoalbuminemia in response to infection or inflammation is likely due to decreased production by the liver and/or increased vascular permeability that may lead to extravasal accumulation of albumin." (PMID 25430894, 2014).
Hypoalbuminemia (continued). "Although hypoalbuminemia has been linked with susceptibility to various diseases and can be used as a marker of frailty in older people, the general population variation in albumin levels is not routinely used for risk assessment among asymptomatic persons." (PMID 24586121, 2014). "Indeed, there are data suggesting that the use of albumin in patients with hypoalbuminemia may be beneficial." (PMID 16356223, 2005). "However, this is not the sole explanation for the association between serum albumin level and disease progression, because hypoalbuminemia is significantly associated with GFR decline after adjustment for the effects of proteinuria." (PMID 15985177, 2005). "Significant post-hoc deviations were observed only for albumin in the TEPT ≥4 group, with hypoalbuminemia showing fewer-than-expected HAEC cases and normal albumin showing more." (PMID 41505435, 2026). "Overall, patients were predominantly distributed in an intermediate zone, with albumin between 2.0 and 3.0 g/dL and SIC scores between 2 and 4, suggesting a frequent overlap between moderate coagulopathy and hypoalbuminemia." (PMID 40648856, 2025). "The hypoalbuminemia in the blood and the marked distribution of FITC-albumin in the jejunal villi were also observed in the mice." (PMID 40737946, 2025). "This study seeks to determine the correlation between serum albumin and CD4 cell count, and identify the determinants of hypoalbuminemia in PLWHIV." (PMID 40898300, 2025). "While our study identifies a potential cutoff for serum ALB levels that may guide ALB infusion, these findings require validation in randomized controlled trials to determine whether targeted ALB supplementation improves outcomes in sepsis patients with hypoalbuminemia." (PMID 40438354, 2025). "Clinicians should implement daily BUN and albumin monitoring, optimize renal perfusion (maintaining MBP ≥ 65 mmHg), and initiate high-protein enteral nutrition within 24 h to correct hypoalbuminemia." (PMID 40547500, 2025). "A large-scale U. S. study demonstrated a notable correlation between lower serum albumin levels and reduced BMD, with the duration of hypoalbuminemia strongly correlating with the severity of BMD deterioration." (PMID 40661684, 2025). "Hypoalbuminemia has been found to predict worse OS, PFS, increased complications, and poor chemotherapy response in HCC.39ȓ41 Normal albumin levels are also needed to decrease the spread of HCC." (PMID 40290253, 2025). "During hospitalization, lower limb infection improved with antibiotics, and albumin, IVIG, and PPI were administered for hypoalbuminemia-related edema, with partial symptomatic improvement." (PMID 41041446, 2025). "Median serum albumin was 4.6 g/dL (IQR: 2.5–5.2), and hypoalbuminemia, defined as albumin <3.5 g/dL, was present in 21.3% (n = 82) of patients." (PMID 40429579, 2025). "Serum albumin acts as a carrier for MTX in the blood, and hypoalbuminemia is commonly observed in children with leukemia." (PMID 41278262, 2025). "Traditional teaching has linked hypoalbuminemia to higher morbidity and mortality, yet our data indicate that when hypoalbuminemia is promptly corrected, severe TBI patients can achieve outcomes comparable to those with normal albumin." (PMID 41226896, 2025). "The median length of hospital stay was significantly longer in patients with hypoalbuminemia at 10 days (IQR: 7-15), compared to 7 days (IQR: 4-10) in those with normal albumin levels (p=0.006)." (PMID 40161084, 2025). "Although linezolid pharmacokinetics could theoretically be influenced by low albumin levels—potentially increasing the free drug fraction, drug clearance, and Vd—no studies have clearly demonstrated a clinically significant impact, which seems unlikely unless severe hypoalbuminemia (<2 g/L) occurs." (PMID 41463691, 2025).
Hypoalbuminemia (continued). "This striking upward shift suggests that aggressive volume resuscitation and/or albumin supplementation in the ICU corrected initial deficits, virtually eliminating severe hypoalbuminemia by the time of transfer out of intensive care." (PMID 41226896, 2025). "In the Chinese clinical guidelines, the indication for human serum albumin supplementation in patients with cancer is ALB≤30 g/L, while hypoalbuminemia is defined as ALB≤35 g/L." (PMID 39886546, 2025). "Hypoalbuminemia prevalence was high in PLWHIV, and a moderate positive correlation was found between the serum albumin level and the CD4 cell count." (PMID 40898300, 2025). "In addition, a multi-center analysis revealed that hypoalbuminemia at PICU admission was independently associated with increased mortality, longer ICU stays, and higher demand for organ support therapies, underscoring the critical role of albumin in pediatric critical illness." (PMID 40938884, 2025). "This study demonstrates that systemic inflammatory markers (uric acid/albumin ratio, NLR, PLR, SII) and biochemical parameters (hypoalbuminemia, hypolipidemia, elevated urea, INR) are valuable predictors of GI bleeding in AF patients receiving OACs." (PMID 41227038, 2025). "A higher proportion of patients in the hypoalbuminemia group had ASA scores of 4 (33.7% vs. 14.8%) and 5 (12.9% vs. 9.9%), while the normal albumin group had a higher proportion of patients with ASA scores of 3 (51.9% vs. 36.6%) and 1 (6.2% vs. 2%)." (PMID 40161084, 2025). "Lactate reflects tissue hypoperfusion and metabolic stress, while albumin reflects nutritional and inflammatory status; a high LAR thus indicates simultaneous shock and hypoalbuminemia." (PMID 41226896, 2025). "Furthermore, in patients treated with long-term and systemic glucocorticoids, hypoalbuminemia may be exacerbated by several factors, including the promotion of protein catabolism by glucocorticoids, the reduction of hepatic albumin synthesis, and the increase in urinary protein excretion." (PMID 41158450, 2025). "The median serum albumin was 4.0 mg/dL (IQR 3.8–4.2), with 30 patients (2.1%) exhibiting hypoalbuminemia (<3.5 g/dL)." (PMID 40727701, 2025). "Although hypoalbuminemia was more common in this report than in the POLARIX study, the median albumin level in this study was 3.2 g/dL (2.1–4.5) vs 3.7 g/dL (1.7–5.4) in the POLARIX trial." (PMID 39907880, 2025). "The mean albumin level was slightly lower in the Strep-TSS group, with hypoalbuminemia (<3 g/dL) in 71.4% of the patients." (PMID 38406070, 2024). "Hypoalbuminemia is a common complication among patients with chronic kidney disease (CKD), characterized by plasma total protein levels below 60 g/L or albumin levels below 35 g/L." (PMID 39545043, 2024). "Patients were stratified into the following three mGPS categories: 0 (normal CRP and albumin), 1 (elevated CRP or hypoalbuminemia), and 2 (elevated CRP and hypoalbuminemia)." (PMID 39156325, 2024). "After intravenous human serum albumin (HSA) and fresh frozen plasma therapy, her hypoalbuminemia and coagulation were gradually corrected." (PMID 39654230, 2024). "It should be noted that BDL animals receiving the restricted diet did not exhibit impaired liver protein synthesis function, as evidenced by albumin levels, while BDL animals receiving all diets exhibited hypoalbuminemia." (PMID 39061903, 2024). "However, in subjects with moderate liver impairment, adverse reactions such as decreased platelet count (50%) and hypoalbuminemia (25%) had relatively higher occurrence rates, which may be related to the baseline thrombocytopenia and lower albumin levels in patients with moderate liver impairment." (PMID 38990016, 2024). "It was found that the average albumin levels were lower in those patients with POC; furthermore, when compared by categories, it was observed that the frequency of hypoalbuminemia was higher in that group (100% vs. 43.8%, p=0.027)." (PMID 38846234, 2024).
Hypoalbuminemia (continued). "Priming CPB circuits with human albumin has shown its benefit on COP and extravascular lung water, suggesting a possible hypoalbuminemia effect on pleural effusion development." (PMID 39336439, 2024). "Further analysis showed that the lower the patient’s albumin level, the higher the incidence of HAP (hypoalbuminemia < 3.0 g/dL: OR = 3.03 vs. hypoalbuminemia < 3.5 g/dL: OR = 2.68)." (PMID 38166762, 2024). "Dogs with hypoalbuminemia pre-treatment and 4 weeks post-treatment tended to have a shorter MST than those with normal serum albumin concentrations." (PMID 38595652, 2024). "Our study highlights dyspnea, chest pain, serum albumin, and an NLR level exceeding 5.5 upon admission, along with hypoalbuminemia and neutrophilia at the time of echocardiography, as significant predictors of moderate to severe PE in CKD patients." (PMID 38843270, 2024). "Li+sick dogs with hypoalbuminemia had higher MLR (median = 0.450; range = 0.3–0.7; 25th–75th percentile = 0.325–0.575) (P = 0.001) than those with albumin values within the reference interval (median = 0.3; range = 0.0–1.2; 25th–75th percentile = 0.2–0.4)." (PMID 39444011, 2024). "Dogs with AHDS and hypoalbuminemia (n = 13; mean: 134; range: 26–246) had significantly higher SIC levels (p = 0.02) compared to dogs with albumin concentrations within the reference range (n = 8; mean: 42; range: 9–84)." (PMID 38540064, 2024). "Hypoalbuminemia was also a risk factor for TD in a study of dogs with immune mediated hemolytic anemia, so decreased serum albumin concentration might directly increase TD risk rather than simply correlating to other risk factors or being a marker of more severe disease." (PMID 38147488, 2024). "In summary, serum CRP and albumin levels act as reliable biomarkers, while high serum CRP and hypoalbuminemia are independent prognostic factors in esophageal cancer and can predict the survival of patients with esophageal cancer to a certain extent." (PMID 39070256, 2024). "We also studied the relationship between ECOG PS and hypoalbuminemia, but found that ECOG PS only explained 0.028% of the variance in serum albumin levels." (PMID 38755213, 2024). "While the PEM is related to patients with hypoalbuminemia of <3.5 g/dL and lymphopenia of <1.5 cells/mm3 the PNI is calculated by multiplying albumin and lymphocytes values (10 × ALB g/dL + 0.005 × lymphocyte count cells/mm3)." (PMID 37909883, 2023). "However, other studies have suggested that hypoalbuminemia is simply a reflection of a negative acute-phase response and that serum albumin levels may be more indicative of underlying inflammation than nutritional status, especially in CKD." (PMID 37828481, 2023). "For SAP patients with hypoalbuminemia, a PSM analysis was further performed to explore the relevant effect of human serum albumin infusion on patient outcomes." (PMID 37277756, 2023). "It was found that the probability of MACE in the hypoalbuminemia group was higher than that in the normal albumin group, and the probability of MACE increased with the increase of the severity of hypoalbuminemia." (PMID 37206105, 2023). "Higher values of NLR and MLR were found both in cats with increased SAA and globulin concentrations and in those with decreased albumin and AGR values, while PLR calculations were higher in cats with hypoalbuminemia." (PMID 37627371, 2023). "With regard to the interaction of albumin and cardiac function, registry data suggested lower LVEF in patients with hypoalbuminemia." (PMID 37108536, 2023). "Median baseline serum albumin levels were 3.01 g/dL (IQR: 2.5–3.7 g/dL), and hypoalbuminemia (<3.5 g/dL) was observed in 66.4% of patients (median baseline serum albumin level: 3.01 g/dL, IQR: 2.5–3.7 g/dL)." (PMID 37508279, 2023). "In addition, infusing albumin may decrease mortality for hypoalbuminemia patients with SAP." (PMID 37277756, 2023).